OR6X1 (olfactory receptor family 6 subfamily X member 1)
Description:
Odorant receptor.
Synonyms: OR11-270
Tractability: Antibody: UniProt places it where antibodies can reach, with medium confidence; UniProt predicts a signal peptide or a membrane-spanning region; its Gene Ontology location is reachable by antibodies, with medium confidence.
Gene: Protein-coding gene on chromosome 11 (123,753,580 to 123,754,518, reverse strand). Ensembl gene ENSG00000221931.
Subcellular location: Cell membrane
Pathways (Reactome):
Sensory Perception: Expression and translocation of olfactory receptors
Gene Ontology:
Molecular function: olfactory receptor activity; G protein-coupled receptor activity
Biological process: detection of chemical stimulus involved in sensory perception of smell; G protein-coupled receptor signaling pathway
Cellular component: plasma membrane; membrane
Genetic constraint (gnomAD): Loss-of-function variants: 0 observed, 0.67 expected, observed/expected ratio (o/e) 0, 90% interval 0 to 1.8. That is too few expected variants to judge how well the gene tolerates losing a copy. Missense variants: 345 observed, 386.98 expected, observed/expected ratio (o/e) 0.89, 90% interval 0.82 to 0.98. Synonymous variants: 159 observed, 156.47 expected, observed/expected ratio (o/e) 1.02, 90% interval 0.89 to 1.16.
Homologues: Orthologues: chimpanzee OR6X1 (97% identical), macaque OR6X1 (93% identical), pig OR6X1 (88% identical), dog OR6X1 (86% identical), mouse Or6x1 (85% identical), rat Or6x1 (84% identical), guinea pig OR6X1 (82% identical). Paralogues in human: OR6F1 (47% identical), OR6M1 (47% identical), OR6S1 (46% identical), OR6C4 (46% identical), OR6T1 (46% identical), OR6J1 (46% identical), OR6C3 (45% identical), OR6C75 (45% identical), OR6C2 (44% identical), OR6C65 (44% identical), OR6C1 (44% identical), OR6C76 (44% identical), and 6 more.
Diseases named in the same sentence as OR6X1 in open-access papers:
OR6X1 is named in the same sentence as 2 diseases in open-access papers, as found by Europe PMC text mining. Sharing a sentence is not in itself a finding about the gene and the disease. The quoted sentences say what the papers report.
adenoma (1 paper, 2013). A neoplasm arising from the epithelium. "Third, we found OR6X1 and NMBR, which are involved in olfactory transduction and neuroactive ligand-receptor interaction, respectively, are mutated in the adenoma." (PMID 23301059, 2013).
OR6X1 also shares sentences with these, for which no sentence is quoted: colorectal adenoma (2 papers).